IMPG1 (interphotoreceptor matrix proteoglycan 1)
Description:
Chondroitin sulfate-, heparin- and hyaluronan-binding protein (By similarity). May serve to form a basic macromolecular scaffold comprising the insoluble interphotoreceptor matrix.
Synonyms: IPM150; SPACR; GP147; RP91; VMD4
Tractability: Antibody: UniProt places it where antibodies can reach, with high confidence; its Gene Ontology location is reachable by antibodies, with high confidence; UniProt predicts a signal peptide or a membrane-spanning region.
Gene: Protein-coding gene on chromosome 6 (75,921,114 to 76,072,678, reverse strand). Ensembl gene ENSG00000112706.
Subcellular location: Cell projection, cilium, photoreceptor outer segment; Secreted, extracellular space, extracellular matrix, interphotoreceptor matrix; Photoreceptor inner segment
Subcellular location (Human Protein Atlas): End piece; Microtubules; Mid piece; Plasma membrane; Principal piece; Predicted to be secreted
Gene Ontology:
Molecular function: chondroitin sulfate binding; extracellular matrix structural constituent; heparin binding; hyaluronic acid binding
Biological process: visual perception
Cellular component: gel phase of interstitial matrix; extracellular matrix; photoreceptor inner segment; interphotoreceptor matrix; photoreceptor outer segment
Genetic constraint (gnomAD): Loss-of-function variants: 59 observed, 60.22 expected, observed/expected ratio (o/e) 0.98, 90% interval 0.79 to 1.22. The upper end of that interval is the gene's LOEUF score, 1.22, which puts it in group 5 of 6, group 1 being the genes least tolerant of losing a copy. Missense variants: 731 observed, 730.13 expected, observed/expected ratio (o/e) 1, 90% interval 0.94 to 1.06. Synonymous variants: 284 observed, 265.9 expected, observed/expected ratio (o/e) 1.07, 90% interval 0.97 to 1.18.
Gene-disease validity (ClinGen):
ClinGen rates the evidence that IMPG1 causes each of these diseases.
IMPG1-related dominant retinopathy (autosomal dominant): Definitive. Any retinopathy caused by an autosomal dominant variant in the IMPG1 gene.
IMPG1-related recessive retinopathy (autosomal recessive): Definitive. Any retinopathy caused by autosomal recessive variants in the IMPG1 gene.
Homologues: Orthologues: chimpanzee IMPG1 (96% identical), macaque IMPG1 (95% identical), dog IMPG1 (76% identical), rabbit IMPG1 (76% identical), pig IMPG1 (74% identical), mouse Impg1 (66% identical), rat Impg1 (65% identical), guinea pig IMPG1 (58% identical), tropical clawed frog impg1 (42% identical), zebrafish impg1b (32% identical), zebrafish impg1a (17% identical). Paralogues in human: IMPG2 (30% identical).
Diseases named in the same sentence as IMPG1 in open-access papers:
IMPG1 is named in the same sentence as 20 diseases in open-access papers, as found by Europe PMC text mining. Sharing a sentence is not in itself a finding about the gene and the disease. The quoted sentences say what the papers report.
vitelliform macular dystrophy (6 papers, 2017 to 2025). A rare genetic disorder characterized by macular degeneration in the retina resulting in progressive loss of central vision with retention of the peripheral vision. "Mutations in the genes encoding IMPG1/2 are linked to two distinct diseases: retinitis pigmentosa (RP) and vitelliform macular dystrophy (VMD)." (PMID 39858590, 2025). "Mutations in IMPG1 or IMPG2 are linked to retinal diseases such as retinitis pigmentosa (RP) and vitelliform macular dystrophy (VMD), yet the specific mutations responsible for each condition remain undefined." (PMID 39858590, 2025). "Mutations of IMPG1 and IMPG2 cause vitelliform macular dystrophies and autosomal-recessive RP, respectively." (PMID 40450528, 2025). "In this study we have identified a series of novel mutations in the IMPG1/IMPG2 genes and provide supportive evidence for their causativity in the development of vitelliform macular dystrophy." (PMID 28644393, 2017). "This demarcation between mutations linked to RP or vitelliform macular dystrophy in IMPG1 is not mirrored in IMPG2, where mutations within and outside the SEA domains can generate either pathology." (PMID 36109576, 2022). "However, MST448-II:1 does not exhibit the characteristic features of vitelliform macular dystrophy or RP typically associated with IMPG1 variants, the latter supported by electrophysiological testing showing no rod involvement." (PMID 40269797, 2025).
retinal degeneration (4 papers, 2016 to 2025). Degeneration of the retina. "Taken together, the histological and ultrastructure results show that the accumulation of cellular material in the retina of Impg1−/− mice results in retinal degeneration and cell death." (PMID 36140676, 2022). "Unravelling the molecular processes linking mutations in the IMPG1 and IMPG2 genes to retinal degeneration will be an important task for future experiments." (PMID 28644393, 2017). "The retinal degeneration of the Impg1−/− mouse is not detectable until 9 months of age either by ERG or funduscopy." (PMID 36140676, 2022).
retinitis pigmentosa (4 papers, 2022 to 2025). Retinitis pigmentosa (RP) is an inherited retinal dystrophy leading to progressive loss of the photoreceptors and retinal pigment epithelium and resulting in blindness usually after several decades. "Several pathogenic variants have been reported in the IMPG1 gene associated with the inherited retinal disorders vitelliform macular dystrophy (VMD) and retinitis pigmentosa (RP)." (PMID 36140676, 2022). "Mutations in IMPG1 and IMPG2 have been previously associated with two clinically distinct IRDs, vitelliform macular dystrophy (VMD) and retinitis pigmentosa (RP)." (PMID 36140676, 2022). "In our cohort, we demonstrate three distinct phenotypes as follows: pattern dystrophy in both the monoallelic IMPG1 cases, maculopathy (PD/AVMD) in the monoallelic IMPG2 cases, and retinitis pigmentosa with early maculopathy in biallelic IMPG2 cases." (PMID 41465146, 2025).
Macular dystrophy (3 papers, 2022 to 2025). Macular dystrophy is a nonspecific term for retinal degeneration, generally confined to the macula, usually presumed of genetic origin. "In MST448-II:1, variants in both the ABCA4 and IMPG1 genes were considered potential contributors to the observed macular dystrophy." (PMID 40269797, 2025).
retinal disease (2 papers, 2025). "A majority of the significantly differentially expressed (FC > 2, FDR < 1%) genes show an increase in expression with higher glucose; these include genes involved in retina development (Neurod1, Casz1, and Crxos) or those associated with retinal disease (Impg1/2, Gucy2f, Mpp4, Arl6, and Rp1)." (PMID 40568109, 2025).
benign concentric annular macular dystrophy (1 paper, 2009). Benign concentric annular macular dystrophy (BCAMD) is a progressive autosomal dominant macular dystrophy characterized by parafoveal hypopigmentation followed by a retinitis pigmentosa-like phenotype (nyctalopia and peripheral vision loss) with a bullBs eye configuration. "A Leu579Pro mutation in IMPG1 may have a causal role in benign concentric annular macular dystrophy based on a linkage study of a large Dutch family." (PMID 19421330, 2009).
glaucoma (1 paper, 2021). Increased pressure in the eyeball due to obstruction of the outflow of aqueous humor. "We chose to take a closer look at different proteins that are either already connected to glaucomatous neurodegeneration, e.g., HSP60, or that were of interest but were not previously linked to glaucoma, e.g., IMPG1." (PMID 35053014, 2021). "Interestingly, mass spectrometry of the probes revealed a regulation of certain proteins after S100B immunization, which are not directly linked to glaucoma or RGCs, such as IMPG1 and IMPG2." (PMID 35053014, 2021).
Hypertension (1 paper, 2009). The presence of chronic increased pressure in the systemic arterial system. "The IMPG1 mRNA in SHR rats was 3.12-fold higher than that of WKY rats at 4 weeks prior to the blood pressure elevation in SHR rats, but not at other time points suggesting its potential involvement in the early phase of hypertension development." (PMID 19421330, 2009).
Inherited Retinal Dystrophies (1 paper, 2025). "This study supports the association of IMPG1 and IMPG2 mutations with retinal dystrophies and implies the prevalence of these mutations in IRDs in the Caucasian population for the first time." (PMID 39858590, 2025).
pulmonary diseases (1 paper, 2020). "The other three genetic loci were rs188904275 in JAKMIP2 (p-value = 3.7×10−8), rs184670665 near IMPG1 (p-value = 2.4×10−10), and rs73586669 near OR4E1 (p-value = 2.4×10−8), with JAKMIP2 previously found to be associated with Body Mass Index (BMI) measurements and pulmonary diseases." (PMID 33075057, 2020).
visual disorders (1 paper, 2016). "Eight positively selected genes within the tarsier lineage were implicated in several diseases associated with eye development and visual disorders (BBS2, BFSP2, IDUA, IL1A, IMPG1, RGR, SRD5A3 and TMC8)." (PMID 27708261, 2016).
retinopathy (2 papers, 2024 to 2025). "Herein we characterise the phenotypic and genotypic features of patients with IMPG1/IMPG2 retinopathy and report novel variants." (PMID 41465146, 2025). "Both IMPG1 retinopathy patients were monoallelic: one patient had adult vitelliform macular dystrophy (AVMD) with drusenoid changes while the other had pattern dystrophy (PD), and they presented to clinic at age 81 and 72 years, respectively." (PMID 41465146, 2025). "The identification of novel variants expands the known genetic landscape of IMPG1 and IMPG2 retinopathies." (PMID 41465146, 2025). "Herein we report the phenotypic spectrum and genotypes of thirteen patients with either IMPG1 or IMPG2 retinopathy." (PMID 41465146, 2025). "Several candidate genes associated with CQ/HCQ retinopathy were found with exome sequencing, including RP1L1, RPGR, RPE65, CACNA2D4, EYS, RP1, IMPG1 and ABCA4." (PMID 38548946, 2024). "Both patients with IMPG1 retinopathy were monoallelic and had a PD phenotype on fundus imaging." (PMID 41465146, 2025). "Our patients did not undergo FA, ICGA, or enhanced depth imaging (EDI) OCT, which limits our ability to draw clear conclusions about the relationship between pachychoroid and the adult vitelliform/PD phenotype in IMPG1 and IMPG2 retinopathy." (PMID 41465146, 2025). "These insights improve our ability to diagnose IMPG1 and IMPG2 retinopathy and have important implications for genetic testing, clinical management, and potential future therapeutic strategies." (PMID 41465146, 2025). "The current literature on variability in the phenotype and appearance of IMPG1 and IMPG2 retinopathy remains limited with only small cohort studies having been reported to date." (PMID 41465146, 2025). "EDT testing was not performed in our study but other studies have shown normal EOG but the mfERG amplitudes can be reduced in the central rings in IMPG1 and IMPG2 retinopathy." (PMID 41465146, 2025). "Future studies with longer follow up with familial surveys and segregation studies are required to accurately characterise the natural history of IMPG1 and IMPG2 retinopathies and also identify penetrance in monoallelic individuals." (PMID 41465146, 2025). "This study adds to the phenotypic characterisation of IMPG1 and IMPG2 retinopathies, describing phenotypic variability and exploring genotype–phenotype correlations hereby adding to the current knowledge base and thus aiding diagnosis." (PMID 41465146, 2025).
cancer (1 paper, 2018). A tumor composed of atypical neoplastic, often pleomorphic cells that invade other tissues. "A second set consisted of an additional 15 cancer-related genes (Nf1, Mki67, Mllt4, Fgfr2, Ctnnb1, Fat1, Clp1, Fat4, Arid1a, Nat1, Nat2, Setd2, Impg1, Nbas and Npat)." (PMID 29925311, 2018).
IMPG1 also shares sentences with these, for which no sentence is quoted: cone-rod dystrophy (1 paper); hearing loss (1); night blindness (1); Nystagmus (1); retinal dystrophies (1); Stargardt disease type 1 (1); Usher syndrome (1).